CATSPER3 (cation channel sperm associated 3)
Description:
Pore-forming subunit of the CatSper complex, a sperm-specific voltage-gated calcium channel that plays a central role in calcium-dependent physiological responses essential for successful fertilization, such as sperm hyperactivation, acrosome reaction and chemotaxis towards the oocyte.
Synonyms: CACRC
Tractability: Small molecule: it belongs to a druggable protein family. Antibody: its Gene Ontology location is reachable by antibodies, with high confidence; UniProt predicts a signal peptide or a membrane-spanning region.
Gene: Protein-coding gene on chromosome 5 (134,967,907 to 135,011,696, forward strand). Ensembl gene ENSG00000152705.
Subcellular location: Cell projection, cilium, flagellum membrane
Subcellular location (Human Protein Atlas): Mid piece; Principal piece
Pathways (Reactome):
Reproduction: Sperm Motility And Taxes
Gene Ontology:
Molecular function: voltage-gated calcium channel activity; monoatomic ion channel activity
Biological process: flagellated sperm motility; sodium ion transport; sperm capacitation; spermatogenesis; calcium ion transmembrane transport; monoatomic ion transmembrane transport; monoatomic ion transport; transmembrane transport
Cellular component: sperm midpiece; sperm principal piece; acrosomal vesicle; CatSper complex; plasma membrane; endoplasmic reticulum; membrane
Genetic constraint (gnomAD): Loss-of-function variants: 23 observed, 35.76 expected, observed/expected ratio (o/e) 0.64, 90% interval 0.46 to 0.91. The upper end of that interval is the gene's LOEUF score, 0.91, which puts it in group 3 of 6, group 1 being the genes least tolerant of losing a copy. Missense variants: 462 observed, 510.89 expected, observed/expected ratio (o/e) 0.9, 90% interval 0.84 to 0.98. Synonymous variants: 158 observed, 187.81 expected, observed/expected ratio (o/e) 0.84, 90% interval 0.74 to 0.96.
Homologues: Orthologues: chimpanzee CATSPER3 (99% identical), macaque CATSPER3 (91% identical), dog CATSPER3 (75% identical), pig CATSPER3 (71% identical), rabbit CATSPER3 (70% identical), mouse Catsper3 (65% identical), rat Catsper3 (64% identical), guinea pig CATSPER3 (58% identical). Paralogues in human: SCN3A (29% identical), SCN2A (29% identical), SCN8A (29% identical), SCN1A (28% identical), CACNA1I (28% identical), SCN4A (28% identical), SCN5A (28% identical), SCN9A (27% identical), CACNA1C (27% identical), CACNA1D (27% identical), CACNA1H (27% identical), CACNA1F (27% identical), and 14 more.
Diseases named in the same sentence as CATSPER3 in open-access papers:
CATSPER3 is named in the same sentence as 8 diseases in open-access papers, as found by Europe PMC text mining. Sharing a sentence is not in itself a finding about the gene and the disease. The quoted sentences say what the papers report.
infertile (4 papers, 2017 to 2023). "In mice, congenital ablation of CatSper1, CatSper2, CatSper3 or CatSper4 genes inhibits CatSper currents and sperm hyperactivation and causes infertility, although spermatogenesis and initial motility are unaffected." (PMID 37108159, 2023). "Studies in human patients have been able to detect several deletions and/or mutations in different CATSPER subunits, i.e., CATSPER1, CATSPER2, CATSPER3 or CATSPERE and their association with infertility." (PMID 37108159, 2023). "Jin and colleagues have stated that CatSper3-/- and CatSper4-/-male rats were infertile even they were showing normal mating attitude." (PMID 29492471, 2017). "In their study, they have shown that CatSper3-/- and CatSper4-/-rats were infertile despite their normal sperm count and motility." (PMID 29492471, 2017). "Knockout of CATSPER3 and CATSPER4 in male mice leads to complete infertility due to rapid loss of motility and absence of hyperactivated motility under capacitating conditions." (PMID 37799407, 2023).
oligoasthenoteratozoospermia (2 papers, 2017 to 2022). A form of male infertility that is characterized by a combination of low number or oligozoospermia, poor motility or asthenozoospermia, and abnormal shape or teratozoospermia of sperms. "Further, CATSPER3 gene expression was observed to be decreased in spermatozoa from patients with AZ and oligoasthenoteratozoospermia (OAT), a condition that includes oligozoospermia (low number of sperm), AZ and teratozoospermia (abnormal sperm shape)." (PMID 35886074, 2022). "CatSper3 gene expression has shown a decrease in the asthenozoospermia, teratozoospermia and oligoasthenoteratozoospermia groups compared to the control but no significant change in the oligozoospermia group." (PMID 29492471, 2017).
teratozoospermia (2 papers, 2017 to 2022). "CatSper1, CatSper3 gene expression by teratozoospermia patients were detected as lower compared to the controls (p<0.001, p<0.001)." (PMID 29492471, 2017).
male infertility (1 paper, 2023). The inability of the male to effect fertilization of an ovum after a specified period of unprotected intercourse. "Additionally, CATSPER3 mutations cause male infertility due to the failure of the acrosome reaction, but there were no defects in routine semen parameters." (PMID 37754226, 2023). "In a rat model of CP-induced male infertility, TS effectively restored sperm count, motility, testosterone levels, and the expression of Catsper1, Catsper2, Catsper3, and Catsper4." (PMID 37754226, 2023).
CATSPER3 also shares sentences with these, for which no sentence is quoted: cancer (2 papers); asthenozoospermia (1); Obesity (1); tumor (1).